AHCYL1 (adenosylhomocysteinase like 1)
Description:
Multifaceted cellular regulator which coordinates several essential cellular functions including regulation of epithelial HCO3(-) and fluid secretion, mRNA processing and DNA replication. Regulates ITPR1 sensitivity to inositol 1,4,5-trisphosphate, competing for the common binding site and acting as endogenous 'pseudoligand' whose inhibitory activity can be modulated by its phosphorylation status. Promotes the formation of contact points between the endoplasmic reticulum (ER) and mitochondria, facilitating transfer of Ca(2+) from the ER to mitochondria. Under normal cellular conditions, functions cooperatively with BCL2L10 to limit ITPR1-mediated Ca(2+) release but, under apoptotic stress conditions, dephosphorylated which promotes dissociation of both AHCYL1 and BCL2L10 from mitochondria-associated endoplasmic reticulum membranes, inhibits BCL2L10 interaction with ITPR1 and leads to increased Ca(2+) transfer to mitochondria which promotes apoptosis. In the pancreatic and salivary ducts, at resting state, attenuates inositol 1,4,5-trisphosphate-induced calcium release by interacting with ITPR1. When extracellular stimuli induce ITPR1 phosphorylation or inositol 1,4,5-trisphosphate production, dissociates from ITPR1 to interact with CFTR and SLC26A6, mediating their synergistic activation by calcium and cAMP that stimulates the epithelial secretion of electrolytes and fluid (By similarity). Also activates basolateral SLC4A4 isoform 1 to coordinate fluid and HCO3(-) secretion. Inhibits the effect of STK39 on SLC4A4 and CFTR by recruiting PP1 phosphatase which activates SLC4A4, SLC26A6 and CFTR through dephosphorylation (By similarity). Mediates the induction of SLC9A3 surface expression produced by Angiotensin-2. Depending on the cell type, activates SLC9A3 in response to calcium or reverses SLC9A3R2-dependent calcium inhibition. May modulate the polyadenylation state of specific mRNAs, both by controlling the subcellular location of FIP1L1 and by inhibiting PAPOLA activity, in response to a stimulus that alters its phosphorylation state. Acts as a (dATP)-dependent inhibitor of ribonucleotide reductase large subunit RRM1, controlling the endogenous dNTP pool and ensuring normal cell cycle progression. In vitro does not exhibit any S-adenosyl-L-homocysteine hydrolase activity (By similarity). Functions as a SAH (S-adenosyl-L-homocysteine) sensor that inhibits autophagy through an MTORC1-independent mechanism. Upon SAH binding, interacts with the catalytic domain of PIK3C3, inhibiting its lipid kinase activity and reducing production of phosphatidylinositol-3-phosphate (PtdIns3P), thereby blocking autophagosome formation.
Synonyms: IRBIT; DCAL; XPVKONA; PPP1R78; PRO0233
Tractability: Small molecule: a structure with a bound ligand is known; a high-quality ligand is known; it has a binding pocket of medium quality. Antibody: UniProt places it where antibodies can reach, with high confidence; its Gene Ontology location is reachable by antibodies, with medium confidence. PROTAC: ubiquitination databases record sites on it; its protein half-life has been measured; a small molecule that binds it is known.
Target class: Enzyme
Gene: Protein-coding gene on chromosome 1 (109,984,765 to 110,023,742, forward strand). Ensembl gene ENSG00000168710.
Subcellular location: Endoplasmic reticulum; Cytoplasm, cytosol; Apical cell membrane; Microsome
Subcellular location (Human Protein Atlas): Cytosol
Pathways (Reactome):
Immune System: Antigen activates B Cell Receptor (BCR) leading to generation of second messengers; CLEC7A (Dectin-1) induces NFAT activation; FCERI mediated Ca+2 mobilization; Role of phospholipids in phagocytosis
Signal Transduction: DAG and IP3 signaling; PLC beta mediated events; VEGFR2 mediated cell proliferation
Disease: FCGR3A-mediated IL10 synthesis
Metabolism: Regulation of insulin secretion
Muscle contraction: Ion homeostasis
Gene Ontology:
Molecular function: identical protein binding; protein binding; adenosylhomocysteinase activity; enzyme regulator activity
Biological process: angiotensin-activated signaling pathway; positive regulation of apoptotic process; positive regulation of sodium ion transport; regulation of mRNA 3'-end processing; response to calcium ion; S-adenosylmethionine cycle; epithelial fluid transport
Cellular component: endoplasmic reticulum; extracellular exosome; mitochondria-associated endoplasmic reticulum membrane contact site; apical plasma membrane; cytoplasm; cytosol; endoplasmic reticulum membrane
Genetic constraint (gnomAD): Loss-of-function variants: 18 observed, 78.41 expected, observed/expected ratio (o/e) 0.23, 90% interval 0.16 to 0.34. The upper end of that interval is the gene's LOEUF score, 0.34, which puts it in group 1 of 6, group 1 being the genes least tolerant of losing a copy. Missense variants: 328 observed, 699 expected, observed/expected ratio (o/e) 0.47, 90% interval 0.43 to 0.51. Synonymous variants: 222 observed, 252.02 expected, observed/expected ratio (o/e) 0.88, 90% interval 0.79 to 0.99.
Homologues: Orthologues: dog AHCYL1 (100% identical), macaque AHCYL1 (100% identical), mouse Ahcyl1 (100% identical), pig AHCYL1 (100% identical), rabbit AHCYL1 (100% identical), rat Ahcyl1 (100% identical), guinea pig AHCYL1 (99% identical), chimpanzee AHCYL1 (93% identical), zebrafish ahcyl1 (90% identical), tropical clawed frog ahcyl1 (85% identical), Drosophila melanogaster AhcyL1 (71% identical), Drosophila melanogaster AhcyL2 (64% identical). Paralogues in human: AHCYL2 (88% identical), AHCY (42% identical).
Diseases named in the same sentence as AHCYL1 in open-access papers:
AHCYL1 is named in the same sentence as 21 diseases in open-access papers, as found by Europe PMC text mining. Sharing a sentence is not in itself a finding about the gene and the disease. The quoted sentences say what the papers report.
cholangiocarcinoma (5 papers, 2016 to 2025). A carcinoma that arises from the intrahepatic biliary tree (intrahepatic cholangiocarcinoma) or from the junction, or adjacent to the junction, of the right and left hepatic ducts (hilar cholangiocarcinoma). "In the cholangiocarcinoma without KRAS mutations, the transcription of AHCYL1 was not abnormal." (PMID 35578598, 2022).
lung carcinoma (4 papers, 2020 to 2025). "By IHC analysis with 90 paired human lung cancer and matched adjacent tissue arrays, we found that AHCYL1 expression level in tumor tissues was relatively higher than that in matched adjacent tissues and positively correlated with PREX2 expression." (PMID 40365293, 2025). "We determined that AHCYL1 regulates tumorigenesis by modulating the cell stemness, thus, highlighting it as a potential prognostic biomarker for lung cancer." (PMID 36872327, 2023). "Altogether, we concluded that AHCYL1 expression is downregulated in undifferentiated stem-like lung cancer cells." (PMID 36872327, 2023). "Meanwhile, AHCYL1 can also regulate cell plasticity to inhibit lung cancer tumorigenesis." (PMID 40365293, 2025). "In other studies, under the stimulation with epidermal growth factor (EGF), AHCYL1 expression is enhanced to maintain the expression of the NBCn1 transporter machinery in the plasma membrane, which plays a positive role in the migration of lung cancer cells." (PMID 40365293, 2025). "Overall, our findings suggested that PREX2 and AHCYL1 played important roles in lung cancer and illustrated a novel regulatory mechanism of PREX2 function by AHCYL1." (PMID 40365293, 2025). "However, the phosphorylation of ERK1/2 and AKT in NL20 was not affected, which suggested that AHCYL1 might employ distinct regulatory mechanisms for cell growth in normal versus lung cancer cellular contexts." (PMID 40365293, 2025).
breast carcinoma (3 papers, 2019 to 2025). "AHCYL1 plays a dual role in tumors; it acts as a tumor suppressor in gastric, ovarian, and breast cancers while promoting chemotherapy resistance in malignant melanoma." (PMID 40584831, 2025). "Fusion partners of FGFR2 reported specifically in breast cancer are AFF3, CASP7 and CCDC6, while partners identified in other cancers include TACC and KIAA family members, PPHLN1, NTRK1, BICC1, AHCYL1, OFD1 and SLC45A3." (PMID 34344433, 2021).
colorectal cancer (3 papers, 2022 to 2025). A primary or metastatic malignant neoplasm that affects the colon or rectum. "IARS2 is a mitochondrial Isoleucyl‐tRNA synthetase, while AHCYL1 is an adenosylhomocysteine hydrolase‐like protein 1, whose expression was proposed to be considered as a novel biomarker for predicting prognosis and immunotherapy response in colorectal cancer." (PMID 40952239, 2025).
ovarian carcinoma (3 papers, 2016 to 2023). A malignant neoplasm originating from the surface ovarian epithelium. "AHCYL1 expression is downregulated in drug-resistant cancer cell lines and also in human ovarian cancer." (PMID 36872327, 2023). "In support of this notion, it was reported that epithelial ovarian cancer patients expressing intermediate to high levels of AHCYL1 showed a greater response to treatments and highest survival rate." (PMID 36872327, 2023).
lung adenocarcinoma (2 papers, 2023 to 2024). A carcinoma that arises from the lung and is characterized by the presence of malignant glandular epithelial cells. "Notably, the tumorigenic effects of lung adenocarcinoma AHCYL1 silenced cells were stronger in male mice, highlighting the potential gender-dependency of AHCYL1 role as a tumor suppressor." (PMID 36872327, 2023).
non-small cell lung carcinoma (2 papers, 2023 to 2025). A group of at least three distinct histological types of lung cancer, including non-small cell squamous cell carcinoma, adenocarcinoma, and large cell carcinoma. "We present a first evidence linking S-adenosylhomocysteine hydrolase-like protein 1 (AHCYL1) as a novel negative regulator of Non-Small Cell Lung Cancer." (PMID 36872327, 2023). "Here, we analyzed the expression of AHCYL1 in Non-Small Cell Lung Cancer (NSCLC) cells from RNA-seq public data and surgical specimens, which revealed that AHCYL1 expression is downregulated in tumors and inverse correlated to proliferation marker Ki67 and the stemness signature expression." (PMID 36872327, 2023).
COVID-19 (1 paper, 2021). A disease caused by infection with severe acute respiratory syndrome coronavirus 2. "The CD16+ monocytes in the mild COVID-19 group expressed higher levels of glycolysis-related genes (PGAM1 and GAPDH), a fatty acid-related gene (HACD4), and an arginine and proline metabolism-related gene (SAT2), as well as lower levels of a cysteine and methionine metabolism-related gene (AHCYL1)." (PMID 33936072, 2021).
tauopathies (1 paper, 2022). "We focused our study on AHCYL1/IRBIT, a protein that modulates IP3R activity and therefore with a potential role in mitochondrial bioenergetics that may be relevant in tauopathies as recently emphasized." (PMID 35218773, 2022).
cancer (10 papers, 2016 to 2025). A tumor composed of atypical neoplastic, often pleomorphic cells that invade other tissues. "In normal control tissues, strong AHCYL1 labeling was observed associated mainly at the epithelial lining of the distal airways (bronchioles), a site proposed for the origin of preneoplastic lesions in adenocarcinoma cancer with the absence or very isolated signals from Ki67 staining." (PMID 36872327, 2023). "In other cancers, the role of AHCYL1 in tumor progression is also distinguished." (PMID 40365293, 2025). "A recent report indicated that AHCYL1 negatively regulates autophagy in U20S and Hela cancer cells." (PMID 36872327, 2023). "However, the role of AHCYL1 during mammalian cell plasticity and cancer progression is still poorly understood." (PMID 36872327, 2023). "In addition, CHPT1, AHCYL1, and CHKB have been demonstrated to be associated with roles that lead to other cancers and affect patient outcomes, although relevant studies are scarce in BC." (PMID 38239641, 2023). "However, as the cancer with the same potential for KRAS/BRAF mutations, the function of AHCYL1 continues to be unknown in CRC." (PMID 35578598, 2022). "These proteins, including AHCYL1, APLP2, CTNN1D, EIF2B1, LGALS1, and SGPL1, play vital roles in maintaining cellular functions such as cell adhesion, protein synthesis, and lipid metabolism, which are often perturbed in cancer cells." (PMID 40090465, 2025). "Previously, we have identified the gene S-adenosylhomocysteine hydrolase-like protein 1 (AHCYL1), also known as IRBIT (Inositol triphosphate (IP3) receptor-binding protein released with IP3) as a potential gene regulated in cancer stem cells using a bioinformatics tool." (PMID 36872327, 2023).
tumor (10 papers, 2014 to 2025). "But, due to the tumor-promoting effect of DH-PH overexpression, the growth inhibitory effect caused by AHCYL1 knockdown in overexpressing DH-PH cells was less than that observed in cells transfected with the empty vector." (PMID 40365293, 2025). "Meanwhile, TCGA database was used to study the connection between AHCYL1 and the tumor immune microenvironment and tumor mutation burden (TMB) in CRC." (PMID 35578598, 2022). "The results of the relationship between the risk score model and tumor immune were similar to the AHCYL1 gene." (PMID 35578598, 2022). "AHCYL1 expression is associated with ovarian carcinogenesis as an oncogene in chickens, however, has a paradoxical effect as a tumor suppressor in human epithelial ovarian cancer." (PMID 33240310, 2020). "Resolving the paradoxical roles of AHCYL1—as both a tumor suppressor and promoter—requires deeper mechanistic dissection." (PMID 40365293, 2025). "For example, we have found that inhibition of AhcyL1 and AhcyL2, enzymes functioning in the methionine metabolic process, potently inhibits fly tumor growth." (PMID 40523311, 2025). "Taken together, these results demonstrate that AHCYL1 mediates the tumor-promoting effect of PREX2 by regulating the binding and mutual inhibition between PREX2 and PTEN in NSCLC cells." (PMID 40365293, 2025). "AHCYL1 silenced cells were subcutaneously injected into the flank of NODscid mice and tumor size and weight were monitored." (PMID 36872327, 2023). "The quantification of spheres/area for other A549 silenced lines, also confirmed that the decrease in the expression of AHCYL1 increases the ability to form tumor spheres." (PMID 36872327, 2023). "To evaluate the relationship between tumor immune microenvironment and the deletion of AHCYL1, we analyzed the different evaluation indicators, like the recruitment of immune cell, TMB, TIDE, and the response for the immunotherapy." (PMID 35578598, 2022). "The AHCYL1 gene is required for CNV and has a close association with the tumor immune microenvironment." (PMID 35578598, 2022). "The influence of AHCYL1 in tumor growth and the recruiting ability of CD8+ T cells were verified, respectively, in vivo and in tissues." (PMID 35578598, 2022). "In contrast to in vitro growth, we noticed that silencing AHCYL1 boosted tumor development and raised tumor weight much more than cells expressing ctrl shRNA." (PMID 35578598, 2022). "To investigate the influence of AHCYL1 on tumor development, we implanted HT-29 cells into BALB/C nu/nu mice with or without AHCYL1 knockdown." (PMID 35578598, 2022). "However, the tumor-specific reliance on the PREX2-AHCYL1 axis, as evidenced by different MEK/ERK and PI3K/AKT signaling response in NL20 and NSCLC cells after AHCYL1 knockdown, suggests a potential therapeutic window." (PMID 40365293, 2025). "Tumor size and tumor weight were lower in the AHCYL1 knockdown group." (PMID 40365293, 2025). "AHCYL1's dual roles in ion homeostasis and tumor promotion warrant caution; systemic inhibition could perturb normal cellular physiology." (PMID 40365293, 2025). "The association analysis of AHCYL1 and a tumor marker Ki67 mRNA expression revealed a negative correlation." (PMID 36872327, 2023). "Silencing of AHCYL1 also increased in vivo tumor capacity in H1299 cells." (PMID 36872327, 2023). "Additionally, knockdown of AHCYL1 promoted tumor growth in the CRC mouse model and recruited lower CD8+ T cells in CRC tissues." (PMID 35578598, 2022). "Consequently, AHCYL1 intensifies the tumor-promoting effects of PREX2 in NSCLC." (PMID 40365293, 2025). "Interestingly, we found that knockdown of AhcyL1 and AhcyL2, which potentially elevates S-adenosyl homocysteine hydrolase Ahcy activity, elevated H3K9me3 levels and strongly inhibited dlg mutant tumor growth." (PMID 40523311, 2025). "Therefore, AHCYL1 mediated the tumor-promoting effect of PREX2 in NSCLC cells." (PMID 40365293, 2025).
tumor (continued). "Therefore, the role of AHCYL1 in NSCLC tumor progression is paradoxical." (PMID 40365293, 2025). "We found that AHCYL1 mRNA expression is reduced in the tumor cell population that co-expressed stemness genes, likewise in LUAD patient samples with recurrence, suggesting AHCYL1 expression could be associated with a more differentiated phenotype in lung samples." (PMID 36872327, 2023). "We knocked down the expression of AHCYL1 in H1299 and HCC827 cells and performed cell-based functional assays to determine its contribution to the tumor phenotype." (PMID 40365293, 2025). "In our study, the cell growth inhibition phenotype of AHCYL1 knockdown and the enhancement on the GEF activity of PREX2 suggest AHCYL1 possesses the tumor-promoting effect." (PMID 40365293, 2025). "At the same time, AHCYL1 releases the mutual inhibition between PREX2 and PTEN, thus leading PTEN facility its tumor suppressor function." (PMID 40365293, 2025). "To gain further insight into the pathophysiological role of AHCYL1 in NSCLC cells, we evaluated the impact of AHCYL1 downregulation during tumor development." (PMID 36872327, 2023). "For the estimation of immunotherapy, we also found that in the group of AHCYL1 deletion, patients had higher TIDE values, indicating higher potential of tumor immune evasion, and were less likely to benefit from immunotherapy." (PMID 35578598, 2022). "The tumor-promoting effects of AHCYL1 in NSCLC appear to rely heavily on its partnership with PREX2, as AHCYL1 knockdown specifically disrupts PREX2 GEF related signaling pathways in NSCLC but not in normal lung epithelia cell NL20 with low expression of PREX2." (PMID 40365293, 2025). "Furthermore, silencing of AHCYL1 in NSCLC cell lines and LCSC-enriched spheres allowed us to determine that AHCYL1 plays a role in tumorigenesis by hampering their self-renewal capacity in vitro and tumor growth in vivo." (PMID 36872327, 2023). "Thus, it may be not appropriate to define AHCYL1 simply as an oncogene or a tumor suppressor remote from its specific regulatory mechanism." (PMID 40365293, 2025). "Additionally, the tissues without AHCYL1 have a weaker ability to recruit the natural killer (NK) cell, CD8+ T cells, and tumor-infiltrating lymphocytes (TILs) and response to immunotherapy." (PMID 35578598, 2022).
adenocarcinoma (1 paper, 2023). A common cancer characterized by the presence of malignant glandular cells. "One adenocarcinoma yielded an AHCYL1 staining score equal to 1 (5%); four cases exhibited score 2 (20%); nine cases score 3 (45%); and six cases score 4 (30%)." (PMID 36872327, 2023). "Particularly, AHCYL1 shows a significantly lower expression in recurrences and metastases compared to primary biopsies in LUAD samples, suggesting that adenocarcinoma with higher metastatic potential show lower AHCYL1 expression." (PMID 36872327, 2023).
infection (1 paper, 2025). The state of being infected such as from the introduction of a foreign agent such as serum, vaccine, antigenic substance or organism. "Moreover, RPS5, AHCYL1 and AP2A2, host factors with presumed proviral roles in IAV infection, were enriched upon infection in our system." (PMID 40623098, 2025).
AHCYL1 also shares sentences with these, for which no sentence is quoted: insulinoma (2 papers); malignant melanoma (2); Ataxia (1); atherosclerosis (1); Intellectual disability (1); ovarian adenocarcinoma (1); pancreatitis (1); renal carcinoma (1).